Y_RNA (Y RNA )
Gene: Miscellaneous RNA gene on chromosome 2 (143,897,263 to 143,897,361, forward strand). Ensembl gene ENSG00000200287.
Homologues: Orthologues: chimpanzee Y_RNA (99% identical). Paralogues in human: Y_RNA (86% identical), RNY3P1 (84% identical), Y_RNA (84% identical), Y_RNA (83% identical), RNY3 (82% identical), Y_RNA (82% identical), Y_RNA (81% identical), Y_RNA (80% identical), Y_RNA (79% identical), RNY3P10 (78% identical), Y_RNA (78% identical), RNY3P11 (77% identical), and 90 more.